PRKCD (protein kinase C delta)
Diseases named in the same sentence as PRKCD in open-access papers (continued):
Sharing a sentence is not in itself a finding about the gene and the disease.
Parkinson disease (3 papers, 2008 to 2014). A progressive degenerative disorder of the central nervous system characterized by loss of dopamine producing neurons in the substantia nigra and the presence of Lewy bodies in the substantia nigra and locus coeruleus. "Thus, PRKCD’s role in mediation and promotion of apoptotic cell death is considered to be critical in the pathogenesis of neurodegenerative disorders, such as Parkinson’s disease." (PMID 23469041, 2013).
Stroke (3 papers, 2015 to 2025). Sudden impairment of blood flow to a part of the brain due to occlusion or rupture of an artery to the brain. "Protein Kinase C Delta (PRKCD) has been implicated in mediating ischemic and reperfusion damage in stroke-reperfusion." (PMID 38653998, 2024).
acute myocardial infarction (2 papers, 2011 to 2022). Necrosis of the myocardium, as a result of interruption of the blood supply to the area. "A TAT-fusion peptide inhibitor of protein kinase C delta(KAI-9803) showed promise in a clinical trial of myocardial infarct size reduction.Additional clinical trials are underway for treatment of ischemic stroke andneurodegenerative disease using KAI-9803." (PMID 21339825, 2011).
Alzheimer disease (2 papers, 2021 to 2024). A progressive, neurodegenerative disease characterized by loss of function and death of nerve cells in several areas of the brain leading to loss of cognitive function such as memory and language. "Protein Kinase C Delta (PRKCD) is associated with a dysregulated Fc Gamma Receptor-mediated phagocytosis pathway in Alzheimer’s disease." (PMID 34182925, 2021).
brain ischemia (2 papers, 2015 to 2022). Diminished or absent blood supply to the brain caused by obstruction (thrombosis or embolism) of an artery resulting in neurologic damage. "PRKCD mediates cerebral reperfusion injury, and Fyn mediates PSD-95Y523 phosphorylation, which may be responsible for the excitotoxic signal cascades and neuronal apoptosis in the brain ischemia and Aβ neurotoxicity." (PMID 35432563, 2022).
celiac disease (2 papers, 2016 to 2026). An autoimmune genetic disorder with an unknown pattern of inheritance that primarily affects the digestive tract. "Another feature of celiac disease is the presence of autoantibodies directed against tissue transglutaminase (tTGA), the serological marker for the disease as well as to protein kinase C delta (PRKCD)." (PMID 27483138, 2016).
complement deficiencies (2 papers, 2016 to 2021). "With the exception of DNase1, DNase1L3, PRKCD deficiencies and complement deficiencies (for which no information on IFN expression is available), an increase in type I IFN activity was documented in the most part of affected patients." (PMID 27260006, 2016).
epilepsy (2 papers, 2021 to 2024). A brain disorder characterized by episodes of abnormally increased neuronal discharge resulting in transient episodes of sensory or motor neurological dysfunction, or psychic dysfunction. "Another gene identified in our study, PRKCD (PKCδ, Protein Kinase C Delta), is involved in the epilepsy inflammatory response and has been shown to increase neuronal excitability and epileptogenesis." (PMID 38166692, 2024). "Fyn phosphorylates protein kinase C delta (PKCδ) which leads to the translocation of nuclear factor-kappa (NFκB) to the nucleus and transcription of key proinflammatory cytokine genes and the production of reactive oxygen species in both PD and epilepsy models." (PMID 34720886, 2021).
fatty liver disease (2 papers, 2014 to 2018). A reversible condition wherein large vacuoles of triglyceride fat accumulate in liver cells via the process of steatosis. "Protein kinase C delta (PKCδ) has been implicated in fatty liver disease and is activated in the methionine and choline-deficient (MCD) diet model of NASH, yet its pathophysiological importance towards steatohepatitis progression is uncertain." (PMID 24454937, 2014).
gastric cancer (2 papers, 2022 to 2025). A primary or metastatic malignant neoplasm involving the stomach. "Our data revealed a significant decrease in phosphorylation of PRKCD at Y334 upon inhibition of CAMKK2 in gastric cancer cells." (PMID 35646067, 2022).
prostate carcinoma (2 papers, 2020 to 2022). A carcinoma that arises from epithelial cells of the prostate gland. "RNA-Seq and bioinformatics analyses revealed a strong correlation between protein kinase C delta (PKCδ) and mitogen-activated protein kinase pathway activation in prostate cancer." (PMID 32427575, 2020).
rheumatoid arthritis (2 papers, 2023 to 2025). A chronic, systemic autoimmune disorder characterized by inflammation in the synovial membranes and articular surfaces. "According to the results of molecular docking, in the context of rheumatoid arthritis, phytocannabinoids may bind to important target proteins such as PIK3CA, AKT1, MAPK9, PRKCD, BRAF, IGF1R, and NOS3." (PMID 36983855, 2023).
thyroid cancer (2 papers, 2017 to 2024). "Moreover, it could be shown that BAG3 can be phosphorylated at serine 187 by the protein kinase C delta (PKCδ); this modified form of BAG3 then triggers the epithelial-mesenchymal transition and invasiveness of thyroid cancer cells." (PMID 28680391, 2017).
uterine carcinosarcoma (2 papers, 2021 to 2023). A usually aggressive malignant neoplasm arising from the uterine corpus and less often the cervix. "Thymoma revealed intermediate differential expression, and uterine carcinosarcoma showed protein kinase C delta (PRKCD) as the only detected differentially expressed gene, consistent with the GO term analysis." (PMID 37895228, 2023). "It was evidently noted that there was a positive correlation between DCP1A and PRKCD in all cancers, except adrenocortical carcinoma (ACC), uterine carcinosarcoma (UCS) and brain lower grade glioma (LGG)." (PMID 34609335, 2021).
anaplastic cancer (1 paper, 2025). "Regarding the downregulated genes in ATC, three of them, namely PRKCD, CYFIP2, and BLNK, were described to have tumor suppressor activity and their downregulation is in line with the more aggressive behavior that characterizes an anaplastic cancer." (PMID 40965626, 2025).
Aortic dissection (1 paper, 2022). Aortic dissection refers to a tear in the intimal layer of the aorta causing a separation between the intima and the medial layers of the aorta. "New genes (MLX, DAB2IP, EP300, ZFYVE9, PML, PRKCD) were suggested as candidate aortic dissection-associated genes, through correlation analyses performed on the results of a WES study on a cohort of 99 Chinese cases." (PMID 35892496, 2022).
ataxia telangiectasia (1 paper, 2023). Ataxia-telangiectasia is the association of severe combined immunodeficiency (affecting mainly the humoral immune response) with progressive cerebellar ataxia. "Skin and visceral granulomas have been described in several other IEIs with predominance of DNA repair defects including ataxia telangiectasia [AT], Artemis deficiency, Nijmegen-breakage syndrome [NBS], PRKCD deficiency and ligase IV deficiency." (PMID 36891233, 2023).
autoimmune lymphoproliferative syndrome (1 paper, 2015). Autoimmune lymphoproliferative syndrome (ALPS) is a rare, inherited disorder characterized by non-malignant lymphoproliferation, multilineage cytopenias, and a lifelong increased risk of Hodgkin's and non-Hodgkin's lymphoma. "A homozygous mutation located in PRKCD causes an autoimmune lymphoproliferative syndrome, with persistent high EBV DNAemia, low PRKCD protein expression and reduced NK cell cytolysis." (PMID 25430668, 2015).
bladder cancer (1 paper, 2021). "When tested as individual gene, 9 genes from the 11-ARG signature (APOL1, ATG4B, CASP3, ITGA3, P4HB, PRKCD, ULK2, and WDR45) exhibited a significant association between mRNA expression levels and overall survival of bladder cancer patients." (PMID 33925460, 2021). "While higher expression of APOL1, ATG4B, ITGA3, WDR45, CASP3, and PRKCD is associated with favorable survival in human bladder cancer patients, increased ULK2 and P4HB mRNA levels are negatively correlated to overall survival of bladder cancer patients." (PMID 33925460, 2021). "The potential role of BAG1 and PRKCD in bladder cancer has not been reported." (PMID 33925460, 2021).
cardiac amyloidosis (1 paper, 2021). Cardiac amyloidosis is a condition whereby cardiac tissue is infiltrated by amyloid fibrils. "However, the interaction between PRKCD and TTR (transthyretin) was enhanced in the heart and may promote the progression of cardiac amyloidosis in patients with HFpEF." (PMID 34306013, 2021).
cervical squamous cancer (1 paper, 2014). "MiR-181a functions as an oncogene by negatively regulating PRKCD, a promoter of apoptosis, to induce chemoresistance in cervical squamous cell carcinoma cells, and may provide a biomarker for predicting chemosensitivity to cisplatin in patients with cervical squamous cancer." (PMID 24949464, 2014).
Cognitive impairment (1 paper, 2023). Abnormal cognition is characterized by deficits in thinking, reasoning, or remembering. "In addition, PRKCD, RASGRP1, SYNCRIP, CSNK1E, and CBX3 were involved in the regulation of synaptic plasticity and were associated with cognitive impairment caused by neurological diseases." (PMID 37106826, 2023).
colon adenocarcinoma (1 paper, 2022). "Analysis of the TCGA colon adenocarcinoma (COAD) dataset showed that the PRKCD mRNA level was also positively correlated with the VTCN1 (encoding B7-H4) mRNA level." (PMID 35410218, 2022).
corticotroph adenomas (1 paper, 2020). "PRKCD silencing is associated with increased EGFR expression, indicating PRKCD as a possible molecular target for the treatment of corticotroph adenomas." (PMID 33574795, 2020). "miR-26a is overexpressed in corticotroph adenomas, and one of its direct targets is protein kinase Cδ (PRKCD)." (PMID 33574795, 2020).
endometrial cancer (1 paper, 2020). Primary or metastatic malignant neoplasm involving the endometrium (mucous membrane that lines the endometrial cavity). "The estrogen signaling pathway, which is highly associated with the development of endometrial cancer, showed enrichment of four differentially expressed ARGs (ITPR1, FOS, PRKCD, and BCL2)." (PMID 33109128, 2020).
hepatic cirrhosis (1 paper, 2019). "In particular, a potential regulatory mechanism by which protein kinase C-delta (PKCδ ) affects profibrogenic gene expression involved in hepatic cirrhosis has never been explored." (PMID 31533364, 2019).
Hyperglycemia (1 paper, 2020). An increased concentration of glucose in the blood. "Hyperglycemia mediates oxidative stress; Protein kinase C-delta expression; production of reactive oxygen species and advanced glycation end-products, which induce hepatic inflammation; DNA damage; and carcinogenesis." (PMID 32785012, 2020).
influenza infection (1 paper, 2013). "CREBBP, PRKCD are implicated in MAPK signaling which is crucial for viral protein production and export while PRKAG2 is implicated in post-entry processes and autophagy in influenza infection." (PMID 24116168, 2013).
ischemia (1 paper, 2022). A hypoperfusion of the BLOOD through an organ or tissue caused by a PATHOLOGIC CONSTRICTION or obstruction of its BLOOD VESSELS, or an absence of BLOOD CIRCULATION. "There were 10 active constituents against ICVD, including quercetin, luteolin, kaempferol, and naringenin, and 10 important targets for anticerebral ischemia, namely, PIK3CA, APP, PIK3R1, MAPK1, MAPK3, AKT1, PRKCD, Fyn, RAC1, and NF-κB1." (PMID 35432563, 2022).
ischemic cardiomyopathy (1 paper, 2026). Ischemic cardiomyopathy is a cardiomyopathy in which a weakness in the muscle of the heart due to inadequate oxygen delivery to the myocardium with coronary artery disease being the most common cause. "The hub genes, including STAT3, MDM2, LRP1, IRS2, PRKCD, CCND2, and CISH, were validated to be highly expressed in adipocytes in ischemic cardiomyopathy patients with end-stage heart failure." (PMID 41869532, 2026).
metastatic cancer (1 paper, 2020). A carcinoma which has spread from the original site of growth to another anatomic site. "MRNAs PRKCD, PRKAR1A, BTG2 competed with lncRNA RP11-408O19.5 for the same miRNAs (miR-15a-5p, miR-15b-5p, miR-16-5p, miR-195-5p) in primary cancer; lncRNA RP11-408O19.5 competed with GGA3 for miR-15b-5p, miR-16-5p, and miR-195-5p in metastatic cancer." (PMID 33614509, 2020).
migraine (1 paper, 2024). "Protein kinase C-delta gene deficient mice do not demonstrate migraine-like responses after nitroglycerin administration, suggesting protein kinase C—delta neurons in the parabrachial nucleus and central nucleus of the amygdala, may play a role in chronic migraine development." (PMID 38481473, 2024).
myocardial ischemia (1 paper, 2022). A disorder of cardiac function caused by insufficient blood flow to the muscle tissue of the heart. "It was reported that the protein kinase C-delta (Prkcd) was upregulated post-AMI and mediated the myocardial ischemia/reperfusion injury and remodeling." (PMID 35346355, 2022).
pheochromocytoma (1 paper, 2019). "Similarly, mutations only associated with pheochromocytoma severely affect the DGKZ, PRKCI, PRKCD and PRKCZ kinase binding interfaces, further suggesting a link between hypoxia sensing and phosphorylation-mediated signaling." (PMID 30943211, 2019).
pituitary tumor (1 paper, 2023). A benign or malignant neoplasm affecting the pituitary gland. "The relevance of PRKCD in growth regulation of ACTH-secreting pituitary tumor cells was firstly highlighted by a study demonstrating that high PRKCD levels, under the control of miR-26a, delay cell cycle in G1 phase." (PMID 37233978, 2023). "Among PRKC proteins, the delta isoform (PRKCD) controls viability and cell cycle progression of an "in vitro" model of ACTH-secreting pituitary tumor, the AtT-20/D16v-F2 cells." (PMID 37233978, 2023). "Recent studies demonstrated that the delta isoform of protein kinase C (PRKCD) controls viability and cell cycle progression of an in vitro model of ACTH-secreting pituitary tumor, the AtT-20/D16v-F2 cells." (PMID 37233978, 2023). "Our results provide new insights into potential PRKCD contribution in Pasireotide mechanism of action and suggest that PRKCD might be a possible marker of therapeutic response in ACTH-secreting pituitary tumors." (PMID 37233978, 2023).
rhabdoid tumor (1 paper, 2022). An aggressive malignant embryonal neoplasm usually occurring during childhood. "In our study, the zebrafish embryo model of the rhabdoid tumor sample harboring the typical SMARCB1 deletion and a PRKCD (protein kinase C delta) mutation responded best to the EZH2 inhibitor tazemetostat and the multi-kinase inhibitor ponatinib out of 11 tested drug hits." (PMID 35159116, 2022).
schizophrenia (1 paper, 2025). A major psychotic disorder characterized by abnormalities in the perception or expression of reality. "The mechanisms underlying the influence of ALAS1, DNAH1, and PRKCD on schizophrenia are attributed to their proximity to TSS/TES." (PMID 39905509, 2025). "As for the PRKCD gene, it has been reported to exert an influence on schizophrenia." (PMID 39905509, 2025).
steatosis (1 paper, 2022). Increased lipid within the cytoplasm of cells. "PRKCD modulates SERCA (Sarco/endoplasmic reticulum calcium ATPase) activity in the human liver cell line (LO-2) induced with palmitic acid, an in-vitro model for steatosis." (PMID 35405942, 2022).
cancer (42 papers, 2007 to 2026). A tumor composed of atypical neoplastic, often pleomorphic cells that invade other tissues. "PRKCD has been linked to several cancers, but its role in MM is unclear." (PMID 41596441, 2026). "Similarly, we observed that PRKCD knockdown inhibited the malignant biological behavior of TNBC cancer cells, which were closely associated with Src and p38 activity." (PMID 38347536, 2024). "The observed high PRKCD mRNA levels in PCa metastases, which may reflect ligand-independent AR activation, possibly play a role in late stage disease because PRKCD is implicated in growth, migration and invasion of cancer cells, including PCa." (PMID 17553165, 2007). "Protein kinase C delta (PKCδ), a serine/threonine kinase involved in cell proliferation, growth, and cancer progression, has been proposed as a prognostic marker in solid tumors, but its role in DLBCL remains underexplored." (PMID 41727647, 2026). "The difference of PRKCD level between cancer tissues and normal tissues was the largest, which accounted for 74.4% (35 pairs) of all included patients." (PMID 38347536, 2024). "PRKCD has been reported to promote survival and proliferation of transformed cells and tumor in a mouse models of cancer." (PMID 38347536, 2024). "First of all, we analyzed the expression of PRKCD in pan-cancer by using the GTEx and TCGA databases and found that in most solid tumors, the expression of PRKCD in tumor tissues was higher than that in normal tissues." (PMID 36816970, 2023). "Many studies have identified several leaderless cytoplasmic proteins in the culture media of cancer cells, including protein kinase C delta (PKCδ), importin α1, and HSP90." (PMID 37241771, 2023). "Protein kinase C-delta inactivation inhibits the proliferation and survival of cancer stem cells in culture and in vivo." (PMID 36293264, 2022). "A pan-cancer analysis was carried out using the 32 other types cancers data from TCGA as the internal verification to further investigate the expression of DCP1A in a variety of cancers and its correlation with the target gene PRKCD." (PMID 34609335, 2021). "The monoallelic loss was most prevalent in PRKCD, then PRKCH, PRKCZ, and PRKCQ across many cancer types compared to other genes." (PMID 35174160, 2021). "The monoallelic loss was most prevalent in PRKCD, PRKCH, PRKCZ, and PRKCQ across different cancer types." (PMID 35174160, 2021). "The correlation between eRNA DCP1A and its predicted target gene PRKCD in different types of cancer was also verified." (PMID 34609335, 2021). "Several studies have identified rottlerin as an inhibitor of PKC-δ (protein kinase C-delta) in human cancers." (PMID 27999199, 2017). "KRAS-activated PRKCD promotes growth, invasion, and migration of cancer cells, through MAPK signalling in NSCLC cell lines (and mouse model), whereas PRKCD activation in cells without active KRAS leads to tumour suppression." (PMID 29062084, 2017). "However, in several cancer cell lines, Apigenin-induced DNA damage has been described to be independent of ROS or caspase activity but mediated by p38 and protein kinase C-delta (PKCδ)." (PMID 38791608, 2024). "Then we knocked down the expression of intracellular PRKCD and found that PRKCD silencing could significantly suppress the proliferation, invasion, and migration abilities of cancer cells." (PMID 36463115, 2022). "In addition, DCP1A was positively correlated with expression of PRKCD in all cancers except ACC, USC, and UGG." (PMID 34609335, 2021). "Besides, PRKCD, PRKCH, PRKCZ, and PRKCQ were associated with varying degrees of low-level CNGs along with different cancers." (PMID 35174160, 2021).